CCL24 (C-C motif chemokine ligand 24)
Diseases named in the same sentence as CCL24 in open-access papers (continued):
Sharing a sentence is not in itself a finding about the gene and the disease.
tumor (continued). "Furthermore, ELISA of the HCT116 cell culture supernatant yielded comparable results, suggesting that CCL24 may have originated from tumor cells within the TME." (PMID 40397411, 2025). "Therefore, tumor cell‐derived CCL24 promotes tumor progression." (PMID 40397411, 2025). "Addition of cyclic rhCCL24 chemokines promoted tumor progression in LOVO mCRC animal experiments, which further suggested that CCL24 promoted tumor progression." (PMID 40397411, 2025). "CCL11 and CCL24 are expressed at lower levels in glandular cells than in stromal cells in CRC tissues, which promotes tumor development." (PMID 37014331, 2023). "M2-Mφs suppress tumor immunity and accelerate tumor progression by secreting immune suppressive factors, such as cytokines (TGF-β and IL-10) and chemokines (CCL2, CCL17, CCL22, and CCL24)." (PMID 35155237, 2022). "Almost all tested parameters (CCL11, CCL24, and CCR3) showed higher SE than commonly used tumor marker CA 19-9." (PMID 34204490, 2021). "Of the cytokines analysed, nine (CD30L, CCL11, CCL24, IGFBP5, IL-4, IL-13, MIP-3ß, CXCL4 and TPO) were significantly more abundant in 4T1 primary tumours than in 67NR primary tumours (Fig. 4aiii)." (PMID 33795809, 2021). "Migration to the TME can be mediated by eotaxins (eotaxin-1/CCL11, eotaxin-2/CCL24, eotaxin-3/CCL26) that bind the CCR3 receptor highly expressed on eosinophils and by alarmins (i.e., HMGB1 and IL-33) released from dying tumor cells." (PMID 33329534, 2020). "Chemokines in the omental tumor tissues revealed some changes as follows: 1) the decreased levels in CCL26, CCL28, CXCL1-3, CXCL8 and CXCL16; 2) the increased level in CCL24; and 3) the conserved level in CCL20 compared to the parental cells." (PMID 27723802, 2016). "M2a macrophages can promote the recruitment of eosinophils and basophils by secreting CCL24 and CCL17, and can promote tumor cell migration." (PMID 26684869, 2015). "Notably, treatment-induced tumor volume reduction correlated with decreased levels of CCL-2, CCL-7, and CCL-12 and increased levels of CXCL-10, CCL-24, CXCL-12, and IL-3." (PMID 38575562, 2024). "High-throughput single-cell RNA sequencing (scRNAseq) revealed that PAZ@Fe-MOF significantly reduced pro-tumorigenic M2-like macrophage populations at tumor sites and suppressed M2-type signaling pathways, such as ATF6-TGFBR1-SMAD3, as well as chemokines including CCL17, CCL22, and CCL24." (PMID 39033109, 2024). "Notably, our computational analysis of this high-dimensional data suggests that the key changes correlating with inhibition of tumor growth include the downregulation of CCL-2, CCL-7, CCL-12, and the upregulation of CXCL-10, CCL-24, CXCL-12 and IL-3." (PMID 38575562, 2024). "ROS also initiated the inflammatory reaction by the NF-κB pathway to secrete chemokines both in tumor cells and the tumor microenvironment, such as CCL2, CCL3, CXCL2, and CXCl12, which were upregulated by Se-PC PDT, and CCL24 and CXC17, which were downregulated by Se-PC PDT in the tumor niche." (PMID 37994159, 2023). "Increased secretion of IL-6, TNFα, CCL2, CCL5, CXCL9 and GM-CSF, which are pro-inflammatory factors combined with decreased secretion of anti-inflammatory factors including IL-4, IL-28A, CCL24, CXCL12 and SCF from infected HEL299 fibroblasts, is expected to be tumor-promoting and enhance metastasis." (PMID 34575976, 2021). "This is the first case showing eotaxin-2 (CCL24) expression on HS neoplastic cells themselves, which may induce eosinophil migration in the tumor tissue." (PMID 33436014, 2021). "In addition, SKCXCR2-derived tumor tissues maintained high CCL20 mRNA expression and induced greater CCL24 and CXCR4 compared to SKCXCR2 cells, indicating the shift of chemokine network during the peritoneal spreading of tumor cells via interaction with other cell types in tumor microenvironment." (PMID 27723802, 2016).
tumor (continued). "CCL24 did not directly alter CD8+ T cell populations; instead, CCL24+ tumor cells recruited CCR3+ TAMs, which promote immunosuppression by promoting nuclear translocation of YAP1, a key transcription factor of the Hippo pathway." (PMID 41694595, 2026). "A difference was found between male mice with and without primary tumor differed in IL-10 and IL-16 levels, which were higher in those with tumor, and in CXCL5, CXCL11, CXCL13, CXCL16, and CCL24 levels, which were higher in those without tumor." (PMID 32545680, 2020). "While no statistical differences in IL-1β, CCL-7, CCL-8, CCL-24 and CXCL-5 gene expression were confirmed among four tumor groups." (PMID 24260500, 2013).
infection (30 papers, 2011 to 2025). The state of being infected such as from the introduction of a foreign agent such as serum, vaccine, antigenic substance or organism. "However, infection reduced the expression of several chemokines upregulated by 4T1, including monocyte recruitment factors Csf1, Ccl3, Ccl6, Ccl9, Ccl24 and EMT-associated Cxcl1." (PMID 40547518, 2025). "We also observed high expression of Ccl24 in the S-2P-vaccinated mice, the gene for eotaxin-2, which is a chemokine responsible for recruiting eosinophils to the site of infection." (PMID 41329757, 2025). "For the first time, we show in this study in relation with submicroscopic infection that the plasma concentration of CCL-24 in the peripheral and placental plasma was significantly higher in healthy controls compared to submicroscopic positive women." (PMID 36689438, 2023). "The TRMs from the eoCre: Il4/13f/f mice displayed significantly lower expression of Mrc1, Ccl24, and Tslp than WT mice after infection, whereas Il4r expression remained unchanged." (PMID 38030609, 2023). "Following low dose challenge, the Ccl24-cre: Tslpf/f mice ameliorated lesion progression and controlled parasite burdens with a 30-fold reduction compared with WT and Ccl24-cre: Tslpf/+ mice at 12 weeks post-infection." (PMID 38030609, 2023). "While IL1R2, IL23R, IL1R1, IL-10, and CCL24 were highly upregulated upon infection of THP-1 macrophages, their expression was barely affected upon infection of primary macrophages." (PMID 34276658, 2021). "Accordingly, we found increased RNA abundance of Arg1, Socs1, Sra1, Saa1, Ciita, Marco, Mgl2, Cd209d, Cd209e, Cd209f, Ccl1, Ccl11, Ccl17, Ccl19, Ccl20, Ccl22, and Ccl24 genes in Stat2−/− mice when compared to WT mice during super-infection." (PMID 30337919, 2018). "In contrast, during infection, the opposite relationship was frequently found, with IL-4, IL-13, CCL5, CCL20 and CCL24 levels associated with less severe reductions in both FVC and FEV1." (PMID 30463560, 2018). "Using genome-wide analyses and murine models of infection we discovered that TPL-2 restricted the expression of Ccl24 and the influx of innate immune cells and T cells in the small intestines of H. polygyrus infected mice." (PMID 28759611, 2017). "Some others such as CCL3, CCR5, CXCL9, CXCL10, CX3CR1 and CCL24 showed a low expression during the infection." (PMID 22905138, 2012). "By 15 min post-H37Rv infection, a decline of 17 cytokines combined with up-regulation of Ccl24 (26.5-fold), Clec4a2 (23.2-fold) and Pparγ (10.5-fold) indicated an anti-inflammatory response initiated by IL-13." (PMID 22039457, 2011). "In contrast, a predominance of downregulated genes related with endothelial injury and the pro-inflammatory response and upregulation of CCL24 in the scrotal skin could indicate a subclinical infection." (PMID 34294155, 2021). "Next, we found increased mRNA expression and activity levels of Arg1, mRNA expression of Fizz, Chi3l3, Cd209d, Cd209e, Mrc2 (Cd206), Marco, Il13, Saa1 (Serum amyloid A1 protein), Ccl17, Ccl19, Ccl20, Ccl22, and Ccl24 in Stat2−/− mice compared to WT mice during super-infection." (PMID 30337919, 2018). "Six genes belonging to the two most significantly over-represented biological processes at the 15 min post H37Rv-infection ‘Immune system response’ (Ifnb1, Il12b, Ccl24, Pparg, and Clec4a2) and ‘Response to stimulus’ (Il13ra1) were selected for verification by RT-QPCR analysis." (PMID 22039457, 2011). "The relative quantification analysis showed a significant increase in gene transcription by 15 min following H37Rv-infection for the Ccl24 (26.5 fold [P<0.001]), Pparg (10.5 fold [P = 0.003]), Clec4a2 (23.2 fold [P<0.001]) genes and the Il12b (12.2 fold [P = 0.002]) gene." (PMID 22039457, 2011).
infection (continued). "Thus, the selective deletion of IL-5+ ILC2s in the R5: Gata3f/f mice, or the conditional ablation of Tslp from dermal TRMs in the Ccl24-cre: Tslpf/f mice, in each case resulted in decreased numbers of ILC2s, eosinophils and dermal TRMs in the lesions, and ameliorated the infection outcome." (PMID 38030609, 2023). "In response to inflammatory stimuli to the chemokines CCL11 (eotaxin-1), CCL24 (eotaxin-2), and CCL5 (RANTES), eosinophils migrate to inflamed tissues or to sites of infection where their survival is prolonged." (PMID 37483591, 2023). "Consequently, we propose the following hypothesis in which the infection using Δgra18 strains, which may provide a weaker Th2 chemokine profile (Ccl17, Ccl22, and Ccl24) led to early control and lower chance for long-term persistence in mice than GRA18 wild type parasites." (PMID 30320549, 2018). "Infection of M2 macrophages with C. pneumoniae resulted in significantly enhanced release of TNF-α, IL-6, IL12p70, IL-12p40, IL-10, CCL17, and CCL24 as compared to uninfected M2 cells." (PMID 26606059, 2015). "Increased expression of Ccl24, CCR3, IL4 and Pdgfc in C57BL/6J mice compared to that in Trim55-/- mice at day four post infection correlates with increased inflammatory cell recruitment and binding to extracellular matrix proteins." (PMID 26452100, 2015). "As CCL24 was produced by the dermal TRMs themselves, the current studies unveil an additional layer of TRM self-maintenance involving their production of TSLP, which was required to maintain the number of IL-5+ ILC2s in the site of infection." (PMID 38030609, 2023). "In addition, RV-C15 infection of mice with allergic airways disease had additive effects on BAL lung IL-13, IL-5 and CCL24 expression, which were greater than induced by RV-A1B." (PMID 33968043, 2021). "We did not observe basophils or eosinophils histologically during infection with C. violaceum, and this was again supported by the absence or low expression of chemokines involved in trafficking of these cell types (i.e. Ccl11, Ccl24, and Ccl26)." (PMID 38352492, 2024).
cancer (23 papers, 2015 to 2025). A tumor composed of atypical neoplastic, often pleomorphic cells that invade other tissues. "Naturally occurring variants were far more common than cancer-associated variants, with (cumulative) interface variant allele frequencies of ~31% (i.e., CCL24) and ~52% (i.e., ACKR1) for the most variable chemokines and receptors, respectively." (PMID 40273912, 2025). "CCL22 and CCL24 have been associated with M2-like polarization and worse prognosis in cancers and were also found to increase upon monocyte encapsulation in NSCLC spheroids." (PMID 34451433, 2021). "Cancer epithelial cells as well as some of CRC cell lines showed high expression levels of CCL24, and CCL24 production by CRC cell lines was modulated by Th1/Th2 cytokines." (PMID 27136535, 2016). "CCL24′s plasma levels have been found to increase in cancer and metastasis." (PMID 38275392, 2023). "In addition, CCL24 was involved in the biological process of cancer through various functions such as angiogenesis and M2 macrophage polarization." (PMID 38075694, 2023). "Seven upregulated genes (≥2.0-fold), Ccl24 (4.8-fold), Ccl17 (3.9-fold), S100a8 (2.9-fold), Tarm1 (2.7-fold), Anxa10 (2.4-fold), Ptgs2 (2.0-fold), and Ccl22 (2.0-fold) were detected as inflammatory and cancer-promoting genes." (PMID 34948416, 2021). "In our study, we found that DM could regulate CCL24 expression in cancer cells." (PMID 35578660, 2022). "Chemokines CCL7, CCL24, and CXCL13, as well as IL-10 and Bmp2, exert pro-tumorigenic effects in a variety of cancers, promoting the invasiveness, metastasis, and stemness of cancer cells." (PMID 38892209, 2024). "Eotaxins (specifically CCL24 and CCL26) have also been correlated to cancer development through M2 macrophage polarization, angiogenesis, invasion and migration, and recruitment of eosinophils." (PMID 39198407, 2024). "In contrast, M2→M1 macrophages reprogrammed in the presence of cancer cell spheroids had increased levels of CCL17 (from M2→M1 45 pg/mL to S + M2→M1 113 pg/mL, p = 0.0021) and CCL24 (from 3.3 to 5 ng/mL, p = 0.0356)." (PMID 37445941, 2023). "Therefore, while the specific role of CCL24 in HL has not been mentioned, the broader understanding of its potential as a biomarker in various cancers and its associations with disease progression and prognosis suggest that it could be a valuable area of investigation for HL as well." (PMID 38275392, 2023). "Unlike M2 macrophages, M1→M2 began to secrete certain IL-4-induced chemokines only after co-culture with cancer cell spheroids, for instance, CCL17 (M1→M2: 0.02 ng/mL; S + M1→M2: 0.12 ng/mL, p = 0.0004) and CCL24 (M1→M2: 0.5 ng/mL; S + M1→M2: 2.4 ng/mL, p = 0.0016)." (PMID 37445941, 2023). "In addition, we found that TAB182 depletion upregulated genes significantly associated with the positive regulation of actin filament polymerization, such as CCL24 and CCL26, which play essential roles in cancer cell invasion and migration." (PMID 37953246, 2023). "Moreover, we found that USP5 showed certain correlation with majority of chemokines with the exception of CCL1, CCL16, CCL27, CCL24 and CCL25 in pan-cancer." (PMID 37268697, 2023). "As the downstream of CCL24, CC chemokine receptor 3 (CCR3) was also involved in many cancer." (PMID 28042950, 2017). "In addition, the secretion of CCL12, CCL22, and CCL24 was higher in the group without cancer cell spheroids (M1), indicating an inhibitory effect of spheroids on these chemokines." (PMID 37445941, 2023).
inflammation (5 papers, 2013 to 2024). Aberrant reaction of the microcirculation characterized by movement of fluid and leukocytes from the blood into extravascular tissues. "Eosinophil: granular leukocytes that are recruited to the lung by IL-5 and C-C chemokines (CCL11, CCL24 and CCL26) to mediate allergen-induced airway inflammation." (PMID 23828644, 2013).
neurodegenerative disease (4 papers, 2017 to 2025). A disorder of the central nervous system characterized by gradual and progressive loss of neural tissue and neurologic function. "Thus, CCL24 as well as CCL11 might be involved in aging-associated neurodegenerative diseases." (PMID 29088099, 2017).
vasculopathy (2 papers, 2023 to 2025). "Altogether, targeting CCL24 has the potential to interfere with inflammation, fibroblast activation, and vasculopathy in patients with SSc." (PMID 39851534, 2025). "Inhibition of CCL24 may offer a multi-faceted approach for SSc treatment, by targeting the main key SSc processes, the vasculopathy, inflammatory, and fibrotic triad." (PMID 37555717, 2023).
bacterial infection (1 paper, 2024). "Eosinophil-attracting chemokines such as eotaxin-1/CCL11, eotaxin-2/CCL24, and eotaxin-3/CCL26 promote host immunity against parasitic and bacterial infection." (PMID 39502090, 2024).
infectious disease (1 paper, 2017). A disorder directly resulting from the presence and activity of a microbial, viral, or parasitic agent in humans. "Several inflammatory conditions and infectious diseases also comprise the selective eosinophil chemotaxis and transendothelial migration mediated by the CC-chemokines eotaxin-1, eotaxin-2 and eotaxin-3 (CCL11, CCL24, and CCL26, respectively) via the eotaxin receptor CCR3." (PMID 29322036, 2017).
CCL24 also shares sentences with these, for which no sentence is quoted: Allergy (8 papers); pancreatic cancer (3); airway hyperresponsiveness (2); autoimmune disease (2); chronic fatigue syndrome (2); chronic obstructive pulmonary disease (2); depression (2); idiopathic pulmonary fibrosis (2); lymphoma (2); pseudoexfoliation glaucoma (2); psoriasis (2); rhinitis (2); Sepsis (2); systemic lupus erythematosus (2); alopecia areata (1); Alzheimer disease (1); atrial flutter (1); carcinoma in situ (1); celiac disease (1); choroidal neovascularization (1); chronic kidney disease (1); chronic rhinosinusitis (1); chronic rhinosinusitis with nasal polyps (1); clear cell renal cell carcinoma (1); colorectal (1); cutaneous T cell lymphoma (1); cytomegalovirus infection (1); dermatitis (1); diabetic eye disease (1); diabetic nephropathy (1).
A further 39 diseases each share a sentence with CCL24 in 1 paper.